DHODH (dihydroorotate dehydrogenase (quinone))
Description:
Catalyzes the conversion of dihydroorotate to orotate with quinone as electron acceptor. Required for UMP biosynthesis via de novo pathway.
Synonyms: DHOdehase; POADS; URA1
Tractability: Small molecule: an approved drug acts on it; a structure with a bound ligand is known; a high-quality ligand is known; it has a high-quality binding pocket; it belongs to a druggable protein family. Antibody: UniProt predicts a signal peptide or a membrane-spanning region. PROTAC: it is named in the literature on targeted protein degradation; ubiquitination databases record sites on it; its protein half-life has been measured; a small molecule that binds it is known.
Target class: Enzyme; Oxidoreductase
Chemical probes: IPP/CNRS-A017 (high quality)
Gene: Protein-coding gene on chromosome 16 (72,008,588 to 72,027,664, forward strand). Ensembl gene ENSG00000102967.
Subcellular location: Mitochondrion inner membrane
Subcellular location (Human Protein Atlas): Mitochondria; Cytosol; Nucleoplasm
Pathways (Reactome):
Metabolism: Pyrimidine biosynthesis
Gene Ontology:
Molecular function: dihydroorotate dehydrogenase (quinone) activity; protein binding; dihydroorotate dehydrogenase activity; oxidoreductase activity, acting on the CH-CH group of donors
Biological process: 'de novo' pyrimidine nucleobase biosynthetic process; 'de novo' CTP biosynthetic process; 'de novo' UMP biosynthetic process; UDP biosynthetic process
Cellular component: mitochondrion; mitochondrial inner membrane; cytoplasm; membrane
Genetic constraint (gnomAD): Loss-of-function variants: 30 observed, 39.35 expected, observed/expected ratio (o/e) 0.76, 90% interval 0.57 to 1.03. The upper end of that interval is the gene's LOEUF score, 1.03, which puts it in group 4 of 6, group 1 being the genes least tolerant of losing a copy. Missense variants: 531 observed, 523.9 expected, observed/expected ratio (o/e) 1.01, 90% interval 0.94 to 1.09. Synonymous variants: 222 observed, 216.21 expected, observed/expected ratio (o/e) 1.03, 90% interval 0.92 to 1.15.
Gene-disease validity (ClinGen):
ClinGen rates the evidence that DHODH causes each of these diseases.
postaxial acrofacial dysostosis (autosomal recessive): Definitive. Postaxial acrofacial dysostosis (POADS) is a type of acrofacial dysostosis characterized by mandibular and malar hypoplasia, small and cup-shaped ears, lower lid ectropion, and symmetrical postaxial limb deficiencies with absence of the fifth digital ray and ulnar hypoplasia.
Homologues: Orthologues: chimpanzee DHODH (99% identical), macaque DHODH (91% identical), rabbit DHODH (91% identical), rat Dhodh (88% identical), mouse Dhodh (88% identical), guinea pig DHODH (86% identical), pig DHODH (77% identical), zebrafish dhodh (68% identical), tropical clawed frog dhodh (67% identical), Caenorhabditis elegans dhod-1 (50% identical), Drosophila melanogaster Dhod (48% identical), zebrafish dpyda.1 (11% identical). Paralogues in human: DPYD (26% identical), FDXR (19% identical).
Diseases named in the same sentence as DHODH in open-access papers:
DHODH is named in the same sentence as 119 diseases in open-access papers, as found by Europe PMC text mining. Sharing a sentence is not in itself a finding about the gene and the disease. The quoted sentences say what the papers report.
melanoma (26 papers, 2012 to 2025). A malignant, usually aggressive tumor composed of atypical, neoplastic melanocytes. "Dihydroorotate dehydrogenase (DHODH), a key enzyme in this pathway, is a promising therapeutic target, but its inhibitors often face resistance in immune-refractory melanoma, linked to low basal stimulator of interferon genes (STING) expression." (PMID 41239499, 2025). "Recent work has implicated DHODH as a regulator of differentiation in myeloid leukemia as well as a promoter of cell cycle progression in some solid cancer types such as melanoma and pancreatic adenocarcinoma." (PMID 31841108, 2019). "DHODH dependency has also been reported in melanoma harboring the BRAF V600E mutation, acute myeloid leukemia, PTEN mutant cells, and K-RAS mutant pancreatic tumor cells." (PMID 31108873, 2019). "Herein, we found that DHODH inactivation/deficiency inhibited melanoma cell proliferation, induced cell cycle arrest at S phase and lead to autophagy in human melanoma cells." (PMID 29348830, 2017). "Recent studies have illustrated that DHODH inhibitors are more effective against malignancies with specific genetic context, such as melanomas carrying BRAF (V600E) mutation and glioblastoma stem cells and breast cancer with PTEN deletion and pancreatic cancer with KRAS mutation." (PMID 33971967, 2021). "In addition, DHODH inactivation or deficiency inhibits melanoma cell proliferation, induces cell cycle arrest at S phase and leads to autophagy in human melanoma cells." (PMID 31889988, 2019). "Immunohistochemistry confirmed a significant upregulation of DHODH in melanoma tissues compared to normal skin, with elevated expression maintained across different disease stages." (PMID 41144149, 2025). "Together, these results indicate that H62 robustly enhances the cytotoxic efficacy of DHODH inhibition in melanoma by integrating STING pathway activation, thereby sensitizing resistant tumor cells to pyroptosis while preserving NK cell viability." (PMID 41239499, 2025). "Inhibiting DHODH has been shown to effectively suppress the growth of melanoma, glioma, small cell lung cancer, and various solid tumors, while also overcoming differentiation blockade in acute myeloid leukaemia." (PMID 41144149, 2025). "Of note, to further explore the potential clinical relevance of the DHODH/STING axis in melanoma immunotherapy response, we performed a bioinformatic analysis using the publicly available TCGA dataset." (PMID 41239499, 2025). "Taken together, these findings indicate that low STING expression contributes to melanoma resistance to DHODH inhibitors." (PMID 41239499, 2025). "In summary, EA6 emerged as a more potent DHODH inhibitor, demonstrating strong tumor regression in melanoma and acting as an NK cells-dependent therapeutic agent." (PMID 41144149, 2025). "In this study, we identified STING expression as a key molecular determinant of melanoma sensitivity to DHODH inhibition." (PMID 41239499, 2025). "Supporting the selectivity of the prodrug, western blot analysis revealed that NK92 cells expressed lower levels of DHODH compared to melanoma cells." (PMID 41239499, 2025). "As anticipated, melanoma tissues exhibited elevated DHODH expression and significantly diminished STING expression relative to non-tumor counterparts." (PMID 41239499, 2025). "This dual-targeting strategy overcomes DHODH inhibitor resistance by coupling metabolic interference with innate immune activation, offering translational potential for melanoma and other treatment-resistant cancers." (PMID 41239499, 2025). "We next examined STING and DHODH expression in human melanoma specimens and matched adjacent normal tissues." (PMID 41239499, 2025). "As expected, cell viability was dramatically reversed after DHODH was silenced in both melanoma cell lines." (PMID 41239499, 2025). "These compelling findings underscore the potential of DHODH as a promising therapeutic target for melanoma treatment." (PMID 41144149, 2025).
melanoma (continued). "In our previous work, we found that the DHODH inhibitor brequinar induces mitochondrial oxidative stress and pyroptosis in melanoma cells, accompanied by enhanced infiltration of natural killer (NK) cells and improved antitumor immunity." (PMID 41239499, 2025). "In this study, we identified low basal expression of STING as a key molecular correlate of resistance to DHODH inhibition in melanoma." (PMID 41239499, 2025). "In melanoma and skin cancers, DHODH supports UV-induced tumorigenesis through STAT3-mediated transcriptional activation, and its inhibition suppresses both primary tumor growth and metastatic progression." (PMID 41369379, 2025). "This presents a major unresolved challenge: how to overcome both metabolic and immunological barriers that limit the therapeutic benefit of DHODH inhibition, especially in immune-cold or treatment-resistant melanoma subtypes." (PMID 41239499, 2025). "We provide proof of concept evidence for combinatorial benefit of DHODH inhibition and immune checkpoint blockade in an aggressive and poorly immunogenic mouse model of melanoma." (PMID 37066260, 2024). "Leflunomide, a DHODH inhibitor, was identified as an inhibitor of neural crest cell development by chemical screening, and A771726 also decreased melanoma cell growth in combination with GREB1 Is4 targeting." (PMID 37658191, 2023). "In zebrafish, expression of a neural crest program defines melanoma initiation, and these cancers are sensitive to leflunomide, a DHODH inhibitor." (PMID 35485397, 2022). "DHODH inactivation inhibits cell proliferation and induces cell cycle arrest at the S phase in BCL-2 (pro-apoptotic) deficient melanoma cells." (PMID 34900699, 2021). "In BRAF (V600E) mutant melanoma cells, DHODH modulates transcriptional elongation and its inhibition completely abrogated cell growth, providing the potential therapeutic strategy through combination of DHODH and BRAF (V600E) inhibitors." (PMID 34123854, 2021). "It was also shown that DHODH is upregulated in melanoma, in which DHODH inhibition leads to a marked decrease in tumor growth both in vitro and in mouse xenograft studies." (PMID 34900699, 2021). "As expected, DHODH-silenced cells resulted into a remarkable S phase arrest in human melanoma cells, compared with the control groups." (PMID 29348830, 2017). "Western blot analysis showed that there was a significantly downregulation of DHODH in these two melanoma cells compared with scramble groups." (PMID 29348830, 2017). "Our results also showed that DHODH inactivation/deficiency induced a persistently increased LC3B expression in A375 and MV3 melanoma cells in a time-course manner." (PMID 29348830, 2017). "Herein, we applied experiments to explore the function of DHODH in melanoma by using both a commonly used clinical DHODH inhibitor leflunomide and shRNAs of DHODH." (PMID 29348830, 2017). "Recent studies reported DHODH inhibition as a promising pharmacological strategy in multiple myeloma, neuroblastoma, melanoma models and acute myeloid leukemia." (PMID 29221122, 2017). "All together, these observations suggested that DHODH inactivation induced autophagy and contributed to cell death in human melanoma cells." (PMID 29348830, 2017). "As expected, DHODH inactivation/deficiency induced significant cell proliferation suppression in human A375 and MV3 melanoma cells." (PMID 29348830, 2017).
melanoma (continued). "Our studies put forward that DHODH inhibition by leflunomide or shRNA knockdown suppressed tumor growth and induced apoptosis and autophagy in melanoma cells." (PMID 29348830, 2017). "Our findings provided evidences for the potential of DHODH used as a drug target for melanoma treatment." (PMID 29348830, 2017). "In our results, DHODH inactivation by leflunomide also induced apoptosis in A375 melanoma cells, and both caspase-9 and caspase-3 were cleaved, which indicating that DHODH inactivation induced intrinsic mitochondrial pathway of apoptosis in melanoma." (PMID 29348830, 2017). "In conclusions, these clues indicated that DHODH deficiency induced autophagy in A375 and MV3 melanoma cells." (PMID 29348830, 2017). "In summary, BCL-2 was a key regulator of autophagy and cell cycle arrest induced by DHODH inhibition in melanoma cells." (PMID 29348830, 2017). "Since malignant melanomas frequently escape immunosurveillance through MHC-I downregulation, rendering them susceptible to NK cell-mediated killing, we investigated whether NK cells contribute to DHODH inhibition-induced anti-tumor immunity in melanoma." (PMID 41144149, 2025). "To define the role of DHODH in melanoma, we first performed a tissue microarray analysis." (PMID 41144149, 2025). "Building on our prior findings that pharmacological DHODH inhibition induces mitochondrial oxidative stress and pyroptotic cell death in melanoma—alongside recruitment of NK cells—we previously developed EA6, a next-generation DHODH inhibitor with enhanced potency." (PMID 41239499, 2025). "Sensitivity to DHODH inhibitors varies substantially among melanoma cell lines." (PMID 41239499, 2025). "Publicly available RNA-seq data from human A375 melanoma cells treated with the clinically approved DHODH inhibitor teriflunomide 38 corroborated our findings, as teriflunomide caused a rapid (within 12 hours) and duration-dependent increase in MHC-I/II and APP transcript levels." (PMID 37066260, 2024). "Publicly available RNA-seq data from human A375 melanoma cells treated with the clinically approved DHODH inhibitor teriflunomide corroborated our findings, as teriflunomide caused a rapid (within 12 hr) and duration-dependent increase in MHC-I/II and APP transcript levels." (PMID 38973593, 2024). "To confirm that BQ- or teriflunomide-mediated APP induction was specifically caused by DHODH inhibition (i.e., on-target effect), we asked whether the effect could be reversed by restoring pyrimidine nucleotides in B16F10 mouse melanoma cells." (PMID 38973593, 2024). "Finally, to examine the role of GREB1 Is4-dependent pyrimidine metabolism in melanoma cell proliferation, the effects of A771726 (DHODH inhibitor) on cell viability in GREB1 Is4 KD melanoma was examined." (PMID 37658191, 2023). "There is increasing evidence that dihydroorotate dehydrogenase (DHODH), an essential enzyme for de novo pyrimidine synthesis, is a promising therapeutic target in various cancer types, including melanoma, acute myeloid leukemia, glioblastoma, lung cancer, pancreatic cancer, and prostate cancer." (PMID 35943801, 2022). "Interestingly, DHODH inhibition with leflunomide has been shown to block neural crest development and decrease melanoma growth in vivo." (PMID 35943801, 2022). "In addition, DHODH inhibition prevents the transcription of genes required for neural crest development and melanoma growth in zebrafish models." (PMID 31108873, 2019). "In conclusions, our data showed that DHODH inhibition by leflunomide or shRNAs suppressed cell proliferation, induced cell cycle arrest at S phase, as well as promoted programmed cell death including intrinsic apoptosis and autophagy in human melanoma cells." (PMID 29348830, 2017). "Our results indicated that combination inhibition of BCL-2 and DHODH might be a new therapeutic regimen for malignant melanoma treatment." (PMID 29348830, 2017).
melanoma (continued). "Importantly, DHODH inhibition by leflunomide induced a significant decrease in melanoma growth both in vitro and in vivo studies." (PMID 29348830, 2017). "Importantly, DHODH inhibition by leflunomide suppressed melanoma formation and growth in both zebrafish and mouse model." (PMID 29348830, 2017). "Our results provided clues for leflunomide and DHODH target used in malignant melanoma treatments." (PMID 29348830, 2017). "To detect whether DHODH knockdown induced apoptosis in melanoma cells, we conducted flow cytometry to analyze apoptosis in DHODH knockdown cells." (PMID 29348830, 2017). "Meanwhile, leflunomide treatment induced cell apoptosis and deficiency of DHODH sensitized cells to drug-induced apoptosis in BCL-2 deficient melanoma cells, while not in BCL-2 abundant melanoma cells." (PMID 29348830, 2017). "Importantly, DHODH seemed to be a potential target in human malignant cutaneous tumors, especially melanoma." (PMID 29348830, 2017). "Likewise, MDA-MB-435S cells were largely unresponsive to uridine supplementation, strongly supporting a DHODH-independent anti-melanoma activity of leflunomide and A771726." (PMID 22815870, 2012). "Notably, inhibition of DHODH resulted in a significant regression of melanoma growth." (PMID 41144149, 2025). "Transcriptomic and proteomic analyses have consistently revealed that DHODH is highly expressed in rapidly proliferating tumors, including hepatocellular carcinoma, colorectal cancer, glioblastoma, neuroblastoma, breast cancer, melanoma, and renal cell carcinoma." (PMID 41369379, 2025). "To address the importance of DHODH in cell proliferation and cell cycle, we used lentivirus carrying small hairpin RNA (shRNA) constructing against DHODH (shDHODH) or a scramble control to infect the human melanoma cells A375 and MV3, then cells were selected by puromycin." (PMID 29348830, 2017). "Interestingly, saturating levels of uridine only modestly rescued A375 cells from the anti-proliferative effects of both leflunomide and A771726, indicating additional mechanism(s), apart from DHODH inhibition are responsible for the anti-proliferative effects of leflunomide in melanoma cells." (PMID 22815870, 2012). "We next evaluated the therapeutic potential of BRQ, a known DHODH inhibitor, in a B16F10 melanoma mouse model." (PMID 41144149, 2025). "Interestingly, while each of the lung, melanoma and breast cancer persister cell types we analyzed here are deficient in one or more anti-ferroptotic factors including NRF2, GSH or in anti-ferroptotic enzymes GPX4, DHODH or VKORC1L1, all were deficient in FSP1." (PMID 40909720, 2025). "We provide proof of concept evidence that pretreatment with DHODH inhibitors can improve the efficacy of immune checkpoint blockade in a highly aggressive and ICB-refractory mouse melanoma model." (PMID 37066260, 2024). "We provide proof-of-concept evidence for combinatorial benefit of DHODH inhibition and ICB in an aggressive and poorly immunogenic mouse model of melanoma." (PMID 38973593, 2024). "We provide proof-of-concept evidence that pretreatment with DHODH inhibitors can improve the efficacy of ICB in a highly aggressive and ICB-refractory mouse melanoma model." (PMID 38973593, 2024). "A study reported that in zebrafish neurons and human melanoma cells, the pol I-binding RNA helicase, DDX21, was localized from the nucleolus to the nucleoplasm by DHODH inhibitors and increased its binding to mRNA." (PMID 36412986, 2022). "On the other hand, our studies and others have revealed that intervention of pyrimidine synthesis by targeting DHODH resulted in decreased protein stability and transcription activity of c-Myc in AML and melanoma." (PMID 34123854, 2021). "To explore the effect of DHODH inhibition by leflunomide, we detected cell growth and proliferation by cell counting method, MTT assay and Brdu assay in human melanoma A375 and MV3 cells after treatment of leflunomide." (PMID 29348830, 2017).